FAS (Fas cell surface death receptor)
Diseases named in the same sentence as FAS in open-access papers (continued):
Sharing a sentence is not in itself a finding about the gene and the disease.
steatosis (28 papers, 2014 to 2025). Increased lipid within the cytoplasm of cells. "In-vivo results showed that hepatic FAS expression was higher in mice with steatosis versus controls and FAS activity was increased in rats with fatty liver." (PMID 38664334, 2024). "In the present study, it is worth noting that hepatic RUNX1 and FAS expression were increased in the steatosis process of patients with MO, but in NASH, their expression was diminished or not increased." (PMID 34063472, 2021). "Studies have found that chronic alcohol intake accelerates steatosis by upregulating FAS and SCD1 activities." (PMID 34819599, 2021). "Treatment with BAR502 caused a ≈10% reduction of b.w., increased insulin sensitivity and circulating levels of HDL, while reduced steatosis, inflammatory and fibrosis scores and liver expression of SREPB1c, FAS, PPARγ, CD36 and CYP7A1 mRNA." (PMID 28202906, 2017). "Likewise, recent evidence shows that sucralose feeding enhances FAS expression in the liver of mice with HFD-induced steatosis via the taste receptor type 1 member 3 (T1R3), a member of the sucralose’s receptor family mediating sweet taste perception." (PMID 36979631, 2023). "The most outstanding finding of the present study is that the liver expression of key genes related to de novo fatty acid synthesis (LXRα, ACC1 and FAS) have an inverse relationship with the grade of steatosis, that is to say, it diminishes when the grade of steatosis increases." (PMID 25474087, 2014). "Moreover, because FGF21 is known to modulate the hepatic metabolic pathway to suppress steatosis, the observed reduced FAS expression and lipid accumulation by E2 and coumestrol in the liver might be associated with increased FGF21 production." (PMID 36839308, 2023). "Interestingly, LXRα, ACC1 and FAS expression had an inverse relation with the grade of steatosis." (PMID 25474087, 2014). "At the hepatic level, TSS and AE worked in concert to attenuate steatosis by downregulating lipogenic genes, such as SREBP-1c and FAS, while upregulating genes involved in lipolysis and β-oxidation, promoting enhanced fatty acid catabolism." (PMID 41141263, 2025). "Conversely, metformin administration attenuated the olanzapine-induced upregulation of PCSK9, FAS, and SCD1 as well as downregulation of SCAD and PPARα, effectively improving hepatic/hepatocyte steatosis." (PMID 35379885, 2022). "On the other hand, PUFAs prevent the liver from steatosis on a basis of SREBP-1c and lipogenic gene (e.g., FAS, ACC, and SCD-1) downregulation and then alleviate the hepatic inflammation by an amelioration of oxidative stress." (PMID 33294458, 2020). "In the hepatic cellular model of steatosis, the expression of fatty acid transport (CD36) and lipogenesis (FAS) genes was inhibited in L-02 cells after 48 h cultured in the FFA mixture and treated with melatonin." (PMID 32093272, 2020). "Our results showed that the infaust change of SREBP-1c, ACC and FAS were markedly ameliorated by UA treatment, indicating that the inhibition of FFA synthesis was also involved in the anti-steatosis role of UA." (PMID 24489777, 2014). "The present study demonstrates that FAS, well known as an important lipogenic enzyme, is overexpressed in the liver of MO NAFLD patients with both simple steatosis and non-alcoholic steatohepatitis, in agreement with other authors." (PMID 25474087, 2014). "By lowering the expression of genes involved in de novo lipogenesis, such as SREBP-1c, FAS, and ACC1, and by guarding against oxidative stress, inflammation, and steatosis—all of which are critical elements in the development of the disease—sililymarin improves lipid metabolism in NAFLD." (PMID 41141263, 2025). "Using steatosis score as the readout, they scanned a panel of anti-NAFLD drugs (positive on animal models), and found inhibitors of ACC, FAS and DGAT2, a FXR agonist, as well as recombinant hFGF19 could efficiently alleviate the steatosis in FFA models and APOB−/−or MTTP−/− models." (PMID 37009924, 2023).
steatosis (continued). "Moreover, after the treatment with the association, the increment in the expression of the genes related to cell survival, AKT1, MAPK8, PIK3CA (four times), and FAS (eight times), and to anti-inflammatory signaling, IL10 (four times), was observed in respect to the steatosis control." (PMID 36770927, 2023). "Hepatic PEPCK and G6Pase mRNA expressions were significantly higher, while GCK and FAS mRNA expression tended to be higher, in the simple steatosis, borderline-NASH and NASH groups than in the no steatosis group." (PMID 29717275, 2018).
leukemia (27 papers, 2009 to 2025). A malignant (clonal) hematologic disorder, involving hematopoietic stem cells and characterized by the presence of primitive or atypical myeloid or lymphoid cells in the bone marrow and the blood. "We have shown before that loss of the INK4A gene changes the sensitivity of leukemia cells to certain apoptotic stimuli, such as glucocorticoid- or FAS-induced apoptosis." (PMID 23828551, 2013). "When miR-196b was over-expressed in leukaemia cells, it represses the function of FAS and at the same time promotes cell proliferation and inhibits apoptosis via increases expression of HOXA9/MEIS1." (PMID 28458781, 2017). "This resulted in the downregulation of several pathways of angiogenesis (FAS, TRAIL, IFN-γ, TNF receptor, and RAC1) in MCF-7 and human Jurkat leukaemia cells." (PMID 38371392, 2024). "We also observed the upregulation of the TNF, TNF receptor member 1 (TNF-R1), and TNF-R member 6 (FAS) genes, and enhanced expression of BAX, an important effector of the extrinsic apoptotic pathway in leukemia cells." (PMID 36294912, 2022). "For example, miR-196b can target either tumour suppressor, FAS or oncogene, HOXA9/MEIS1 in leukaemia." (PMID 28458781, 2017). "Many studies indicate that lipogenesis is required for the growth of cancer cells, which contradicts the marked decrease of FAS, ACC1 and SCD1 (genes that enhance lipogenesis) and accelerated leukemia development upon ChREBP deletion reported here." (PMID 27224916, 2016). "Some of these AM genes are known to be dysregulated in leukaemia: up regulation of BIRC3 and down regulation of APAF1, CIDEB, FAS, TNFRSF25, TNFSF10 were previously identified by our group as specific alterations of AM genes in leukemic cells." (PMID 20642818, 2010). "Another study showed that in mixed lineage leukaemia (MLL)-rearranged leukaemia, miR-196b could directly target left HOXA9/MEIS1 oncogenes and FAS tumor suppressor." (PMID 33611311, 2021). "However, the same effect on splicing could not be observed for MAP2K2, VEGF or FAS in leukemia or HeLa cells, suggesting that different tumor lineages may respond differently to SRPK inhibition." (PMID 26244849, 2015).
ovarian carcinoma (24 papers, 2010 to 2024). A malignant neoplasm originating from the surface ovarian epithelium. "This suggestion is supported by earlier findings revealing an association between the loss of FAS expression and resistance to chemotherapeutic drugs in ovarian cancer cells." (PMID 38256203, 2024). "In this regard, combination treatment with FAS enzyme inhibition associated with standard chemotherapy for the treatment of ovarian cancer resulted in a successful therapy approach both in in vitro and in vivo settings for therapy-resistant ovarian cancer cells." (PMID 35625629, 2022). "Our focus was on elucidating the impact of EZMLD on m6A methylation modification of KRT8 in ovarian cancer cells and its subsequent role in regulating the FAS apoptosis signaling pathway." (PMID 39103890, 2024). "Further study demonstrated that mollugin inhibited cell proliferation and promoted apoptosis of breast and ovarian cancer cells by suppressing FAS expression through modulation of a HER2/Akt/SREBP-1c signaling pathway." (PMID 36160419, 2022). "FAS is the enzyme accounting for the de novo synthesis of fatty acids, and it is highly expressed in many human cancers, including ovarian cancer." (PMID 32974128, 2020). "Enhanced FAS expression is a poor prognostic factor in patients with breast, prostate, and ovarian cancer, generating an intriguing paradigm that cancers with high expression of FAS have a growth and/or survival advantage." (PMID 23110339, 2012). "Enhanced FAS expression is a poor prognostic factor in patients with breast, prostate, and ovarian cancer, generating an intriguing paradigm that cancers with high expression of FAS have a growth and/or survival advantage and selective manipulation of FAS may be novel therapeutic strategy." (PMID 21244676, 2011). "As case study, we quantified expression of MCT1, MCT4, GLS, PHGDH, FAS, and ACC in 17 patient-derived ovarian cancer xenografts and correlated it with survival." (PMID 32974128, 2020). "Similar to what is observed in carcinoma MCF7 cells and ovarian cancer SK-OV-3 cells; reduction in EGF-mediated invasion was observed in FAS siRNA transfected HTR-8/SVneo cells." (PMID 32703964, 2020). "In this ovarian cancer model, IL‐12‐expressing CAR‐T cells increase their expression of first apoptosis signal ligand (FASL) and up‐regulate FAS expression on TAM and thereby eliminate TAM in the ascites via the FAS/FASL apoptosis pathway." (PMID 29963704, 2018). "Annexin A3, P-glycoprotein (P-gp), signal transducer and activator of transcription 3 (STAT3), FAS, DNA methyltransferase-I (DNMT-1), multidrug resistance protein 2 (MRP2), ATP 7A, and ATP 7B are exosomal proteins that promote drug resistance in ovarian cancer cells." (PMID 38796525, 2024). "Similarly, TNF receptor superfamily member 6 (FAS) and OPN are correlated with postoperative complications in ovarian cancer patients." (PMID 37887011, 2023). "Moreover, HO-3867 has been shown to regulate the expression of FAS, FAK, and VEGF in order to suppress metastasis of ovarian carcinoma cells." (PMID 35745828, 2022). "For instance, melittin induced apoptosis via death receptors and inhibited the JAK2/STAT3 pathway in ovarian cancer cells and also promoted apoptotic cell death via the mitochondrial signaling pathway, but not via the FAS/FASL pathway in human gastric (SCG-7901) cells." (PMID 32823904, 2020). "The data from KM-Plotter showed that FAS mRNA expression was not correlated with OS and PFS in ovarian cancer (OS, HR: 0.98 [0.86, 1.11], p=0.74, n=1656 cases; PFS, HR: 0.98 [0.87, 1.12], p=0.8, n=1435 cases)." (PMID 31942177, 2020).
lymphoma (23 papers, 2006 to 2025). A malignant (clonal) proliferation of B- lymphocytes or T- lymphocytes which involves the lymph nodes, bone marrow and/or extranodal sites. "The reduced FAS levels induced by ARID1A loss rendered lymphoma cells resistant to both soluble and T cell membrane-anchored FASLG-induced apoptosis, and significantly diminished CAR T cell killing in functional experiments." (PMID 39843653, 2025). "The FAS rs1800682 (A/G) polymorphism was also shown to be associated with the clinical manifestations of adult T-cell leukemia/lymphoma (ATLL)." (PMID 39859379, 2025). "Overall, our experiments demonstrate that ARID1A loss leads to reduced FAS levels on lymphoma cells, making them more resistant to apoptosis induced by both soluble and membrane-bound FAS ligand, including CAR T cells." (PMID 39843653, 2025). "FAS mutations have also been found in lymphomas, suggesting that FAS may be a tumor suppressor gene." (PMID 40433378, 2025). "This hypothesis aligns with observations in mice, where dysfunctional apoptosis regulation (via FAS mutation) resulted in both autoimmune disease and lymphoma." (PMID 39175752, 2024). "In the original ALPS-associated lymphoma cohort at the National Institutes of Health, 10 of 130 subjects heterozygous for germline FAS mutation developed lymphoma: three (two of B cell origin, one of T cell) were EBV-positive on pathology by in situ hybridization." (PMID 25374737, 2013). "In summary, we have elucidated the molecular mechanism of reduced FAS expression in ARID1A mutant lymphoma cells and demonstrated that this promotes functionally and potentially clinically relevant escape from T cell mediated killing." (PMID 39843653, 2025). "Functional experiments in BCL2-translocated lymphoma cells demonstrated that ARID1A is directly involved in the regulation of FAS, and ARID1A loss leads to decreased FAS protein and gene expression." (PMID 39843653, 2025). "Our results demonstrate that the activation of c-MYC in lymphoma cells drives immune suppression through the downregulation of exosomal miRNA-7e-5p and activation of FAS-mediated apoptosis in macrophages." (PMID 33168041, 2020). "RT-PCR expression profiling of various DLBCL cell lines demonstrated that expression of key enzymes GLUT1, HK2, FAS and Cyt-C was induced during hypoxia in lymphoma cell lines and patient derived malignant B cells." (PMID 29335581, 2018). "Finally, we aimed to directly demonstrate that ETS1 and RUNX3 cooperate in regulating FAS expression in lymphoma cells." (PMID 39843653, 2025). "Regarding their relationship with lymphoma tumor cells, normal and activated B cells from the germinal center express CD95 (also called FAS) to induce apoptosis." (PMID 35326620, 2022). "However, the panel targeted the most relevant genes for lymphoma diagnosis but did not cover all exons for some genes (e.g., KMT2D) and lacked a few select genes (e.g., FAS, SLAMF1, SPEN, and NCOR2), which are described in cutaneous MZL10,32." (PMID 37081015, 2023).
colorectal cancer (22 papers, 2013 to 2025). A primary or metastatic malignant neoplasm that affects the colon or rectum. "Resistance to immunotherapy in colorectal cancer (CRC) is associated with obstruction of FAS (Apo‐1 or CD95)‐dependent apoptosis, a hallmark of cancer." (PMID 38148593, 2024). "A hallmark of human colorectal cancer is lost expression of FAS, the death receptor for FASL of cytotoxic T lymphocytes (CTLs)." (PMID 35053524, 2022). "For example, it was reported that FAS is highly expressed in normal human colon epithelial cells but is down-regulated in human colorectal carcinoma, whereas complete loss of FAS expression is often observed in metastatic human colorectal tumor." (PMID 35053524, 2022). "PIR was significantly upregulated in CRC as compared with corresponding normal tissues according to public TCGA and GEO database, while FAS is downregulated in colorectal cancer." (PMID 38148593, 2024). "In adipocytes FAS signal pathway promotes colorectal cancer lung metastasis and low-grade inflammation." (PMID 39390002, 2024). "This approach has also been successfully applied to discover novel synthetic lethal interactions with the RAS oncogene in colorectal cancer cells and to identify dependency between NfκB, FAS and EGFR pathways in lung cancer." (PMID 37202533, 2023). "Correlation of FAS mRNA expression level with the FAS promoter DNA hypermethylation level revealed that the FAS promoter DNA hypermethylation is inversely correlated with FAS expression level in tumors in human colorectal cancer patients." (PMID 35053524, 2022). "Tumor-selective delivery of FAS DNA nanoparticle is potentially an effective therapy for human colorectal cancer." (PMID 35053524, 2022). "The function of ACAT1, ALDH4A1, and FAS in colorectal cancer has been verified by previous studies, participating in the progression of CRC." (PMID 35992263, 2022). "FAS expression decreases with tumor progression in human colorectal cancer, and the FAS expression level is positively correlated with human colorectal-cancer patient survival time." (PMID 35053524, 2022). "Analysis of single-cell RNA-Seq datasets revealed that FAS is highly expressed in epithelial cells and immune cells but down-regulated in colon-tumor cells in human colorectal-cancer patients." (PMID 35053524, 2022). "Previous study has shown that FAS expression level in tumors with patient survival time indicates that a low FAS expression level is positively correlated with colorectal-cancer patient survival." (PMID 35053524, 2022). "Our findings indicate that FAS expression is repressed by its promoter DNA hypermethylation in human colorectal cancer patients." (PMID 35053524, 2022). "The FAS promoter is hypermethylated and inversely correlated with FAS mRNA level in human colorectal carcinomas." (PMID 35053524, 2022). "FAS is highly expressed in human colon epithelial cells but down-regulated in human colorectal carcinoma." (PMID 35053524, 2022). "DOTAP-Chol-hFAS is therefore potentially an effective agent to restore FAS expression in metastatic human colorectal carcinoma to suppress metastasis." (PMID 35053524, 2022). "Our study showed that miR-196b-5p was down-regulated in both spheroid subtypes while another study showed that miR-196b-5p was specifically up-regulated leading to reduction of apoptosis in colorectal cancer cells by mediating FAS gene expression." (PMID 28717596, 2017). "We identified FAS cell surface death receptor (FAS, also called Apo1 or CD95) as a MIR196B target gene in colorectal cancer and verified their association between MIR196B and FAS in colorectal cancer cells." (PMID 25605245, 2015). "In human cancer, tumor cells tend to downregulate FAS expression to avoid FAS-mediated apoptosis signaling, particularly in metastatic human colorectal cancer." (PMID 25605245, 2015). "In contrast, anti-MIR196B up-regulated FAS expression and increased apoptosis in colorectal cancer cell lines." (PMID 25605245, 2015).